MET (MET proto-oncogene, receptor tyrosine kinase)
Diseases named in the same sentence as MET in open-access papers (continued):
Sharing a sentence is not in itself a finding about the gene and the disease.
viral infection (5 papers, 2020 to 2026). "To examine the functional relevance of LECT2 in viral infection, we evaluated LECT2, MET and HGF mRNA expression in the liver of patients with chronic hepatitis C (CHC)." (PMID 35676290, 2022). "Finally, signaling molecules such as WNT5A, MET, and NETO2 are modulated by bacterial and viral infections (including SARS-CoV-2 and M. tuberculosis) to alter cell survival, inflammation, and proliferation pathways, reinforcing the pathogenic role of these exosome-borne receptors." (PMID 41440381, 2025).
chondrosarcoma (4 papers, 2013 to 2023). A malignant cartilaginous matrix-producing mesenchymal neoplasm arising from the bone and soft tissue. "Compared to cMET inhibitors including crizotinib, capmatinib, and tivantinib, tivantinib was more specific for inhibition of MET, yet chondrosarcoma seems to require higher dose of IC50." (PMID 36622753, 2023).
COVID-19 (4 papers, 2021 to 2025). A disease caused by infection with severe acute respiratory syndrome coronavirus 2. "DNMT3B, LAMC1, MET, NASP, PTEN, and SPARC are upregulated in COVID-19." (PMID 36204652, 2022). "Therefore, although the c-MET can lead to KF-kB activation, this does not seem to be the case in MSCs from severe COVID-19 patients." (PMID 35095855, 2021). "However, the roles of LAMC1, MET, NASP, and SPARC in COVID-19 have not yet been elucidated." (PMID 36204652, 2022).
deafness (4 papers, 2019 to 2025). An inherited or acquired condition characterized by the complete loss of the ability to hear from one or both ears. "Researchers believe that the pharmacological effects of MET inhibitors can lead to an unstable HGF/c-MET signaling pathway, which may cause deafness in patients by disrupting the development of stria vascularis." (PMID 41411333, 2025). "MAP3K1 phosphorylates serine and threonine and functions in a signaling pathway where pathogenic variants of HGF, MET, and GAB1 were previously reported to be associated with human deafness DFNB39, DFNB97, and DFNB26, respectively." (PMID 39062623, 2024). "For example, a dominant variant of METTL13 (DFNM1) completely suppresses recessive non-syndromic deafness DFNB26, associated with a variant of GAB2 with both genes functioning in the HGF/MET signaling pathway." (PMID 32987832, 2020).
dementia (4 papers, 2023 to 2025). Loss of intellectual abilities interfering with an individual's social and occupational functions. "Further supporting this notion, two ongoing phase 2 trials in patients with mild-to-moderate AD dementia (NCT04488419) and Parkinson’s disease (PD) dementia or dementia with Lewy bodies (NCT04831281) are testing a drug targeting HGF and MET." (PMID 39187705, 2024). "Reduced HGF/MET signaling contributes to synaptic pathology in the 5 × FAD mouse model of AD; while FGF2 gene transfer restores hippocampal functions in APP/PS1 mice; CRH (corticotropin-releasing hormone) has been proposed to play important roles in AD and other dementias." (PMID 39234102, 2024). "Activation of the HGF/MET system induces a variety of proneuronal and procognitive processes, and the neurophysiological effects of HGF are well-suited to promote neuronal survival and potentially address the neurodegenerative cascade observed in AD and other types of dementia." (PMID 36538176, 2023). "Significantly associated proteins at a false discovery rate (FDR) < 0.05 in both models 1 and 2 were CGREF1, MET, ALDH2, NECTIN2, APOC1, APOE and FOSB for HFRS, and CDK and POF1B for HFRS without dementia." (PMID 40764432, 2025).
epithelioid sarcoma (4 papers, 2014 to 2024). An aggressive malignant neoplasm of uncertain differentiation, characterized by the presence of epithelioid cells forming nodular patterns. "This reactivation depends on c-MET signaling, which is highly active in epithelioid sarcoma." (PMID 39329778, 2024).
glioneuronal tumor (4 papers, 2020 to 2024). "This is the first case report demonstrating the presence of a CLIP2::MET fusion in two pediatric low-grade glioneuronal tumors (GNT)." (PMID 38650040, 2024). "Overall, in the context of a CLIP2::MET fusion detected by RNAseq, the molecular findings are most consistent with a CLIP2::MET fusion-positive glioneuronal tumor." (PMID 38650040, 2024). "More recently, a novel MC of glioneuronal tumor (called the “glioneuronal tumor, not otherwise specified, subtype A") harboring RTK (ALK, NTRK1, NTRK2, NTRK3, and MET) fusions and MAPK (RAF1) fusions have been isolated by DNA‐methylation profiling." (PMID 37349135, 2023).
heart failure (4 papers, 2020 to 2025). Inability of the heart to pump blood at an adequate rate to meet tissue metabolic requirements. "Interestingly, we found that crizotinib treatment alone apparently increased MET protein levels and it has been reported that sustained activation of MET signaling leads to cardiac remodeling and heart failure." (PMID 37733896, 2024). "MET encoded a receptor tyrosine kinase c-MET for a hepatocyte growth factor (HGF), which was an important target of ginsenoside Rg5 against heart failure." (PMID 36313322, 2022). "The mRNA expression of BCL2L1 and MET was increased after ginsenoside Rg3, ginsenoside Rg5, and pseudoginsenoside F11 treatment, indicating that these three components may protect cardiomyocytes from damage by inhibiting apoptosis to improve heart failure." (PMID 36313322, 2022). "Of note, crizotinib also inhibits other kinases, including MET and ROS1, which may contribute to its toxicity profile which includes heart failure, arrhythmias, and conduction abnormalities." (PMID 40828781, 2025).
interstitial lung disease (4 papers, 2020 to 2025). A diverse group of lung diseases that affect the lung parenchyma. "In summary, these data reveal an association between enhanced c-MET expression in immune cells and interstitial lung diseases, particularly indicating a potential involvement of c-MET expression in T cells underlying the development of the fibrosing condition." (PMID 38909206, 2024). "Herein, we describe a case of patient co-harboring EGFR Ex19del mutation and MET de novo amplification who presented targeted (almonertinib)-induced interstitial lung disease (ILD)." (PMID 40034596, 2025). "Furthermore, c-MET expression was assessed in cryobiopsy sections, bronchoalveolar lavage fluid cells samples and single cell RNA-sequencing dataset from human patients with distinct interstitial lung diseases." (PMID 38909206, 2024).
leiomyosarcoma (4 papers, 2010 to 2017). An uncommon, aggressive malignant smooth muscle neoplasm, usually occurring in post-menopausal women. "In leiomyosarcoma, miR-152 targets the tyrosine-protein kinases: MET and KIT." (PMID 28895916, 2017). "The authors tested Met-pep1 labeled with125I as a diagnostic tracer in vivo in xenografts in mice models of human leiomyosarcoma derived from the cell line SK-LMS-1/HGF, which expresses c-MET/HGF." (PMID 28485003, 2017). "On the other hand, experimental upregulation of miR-152 reduces levels of MET and KIT in leiomyosarcoma cell lines." (PMID 28895916, 2017). "As with leiomyosarcoma, miR-152 is downregulated in UPS and negatively correlates with MET and KIT mRNA levels." (PMID 28895916, 2017).
liposarcoma (4 papers, 2015 to 2024). A usually painless malignant tumor that arises from adipose tissue. "For example, CDK4 is amplified in patients with well-differentiated liposarcoma and de-differentiated liposarcoma, hepatocyte growth factor receptor (MET) is overexpressed in de-differentiated liposarcoma, and SRC is activated in myxoid liposarcoma and pleomorphic liposarcoma." (PMID 29568347, 2018). "Moreover, several low-molecular-weight multi-kinase inhibitors targeting MET, AXL, IGF1R, EGFR, VEGFR2 and PDGFR-β could be effective in the types of liposarcoma characterized by abnormalities in PI3K/Akt/mTOR signaling and the associated deregulation of other cascades." (PMID 38254762, 2024). "Notably, none of the more than 150 liposarcoma samples of any type (i.e., atypical lipomatous tumor, dedifferentiated, myxoid and pleomorphic liposarcoma) showed MET amplification, MET copy number gain or MET or HGF overexpression." (PMID 25844809, 2015).
neutropenia (4 papers, 2015 to 2021). A decrease in the number of neutrophils found in the blood. "Described toxicities associated with inhibition of c-MET related signaling are fluid retention, mucositis, hypophosphatemia, neutropenia, cardiac conduction that were observed in approximately 16% of patients." (PMID 33919702, 2021).
rectal adenocarcinoma (4 papers, 2015 to 2024). "This is the case for rectum adenocarcinoma: its five oncogenes are BCL2, KIT, KLF4, MET, and PDGFRA." (PMID 31900418, 2020).
sarcomatoid carcinoma (4 papers, 2017 to 2021). A malignant epithelial neoplasm characterized by the presence of spindle cells and anaplastic morphologic features. "The MET mutation rate in spindle cell carcinoma was significantly higher than that in pleomorphic carcinoma (P = 0.012, Fisher’s exact test)." (PMID 32985499, 2020). "One adenocarcinoma and one carcinosarcoma, a subtype of sarcomatoid carcinoma, were found to express MET exon 14 skipping mutation transcripts." (PMID 31369639, 2019). "Somatic mutations leading to MET exon 14 splicing have been shown to occur in approximately 3% of NSCLC cases, with a higher frequency observed in primary sarcomatoid carcinomas (SC) of the lung, although reports were based on highly variable cohort sizes and sequencing technologies." (PMID 28418914, 2017).
schwannoma (4 papers, 2013 to 2020). A benign, usually encapsulated slow growing tumor composed of Schwann cells. "We therefore set out to determine whether MET inhibition would be beneficial in a model of NF2-associated schwannoma." (PMID 27363027, 2016). "In schwannomas, MET and its ligand HGF were expressed in all analyzed samples, as determined by qRT-PCR and immunohistochemistry, although no healthy tissue was used as the control; therefore, no alterations of expression were established." (PMID 23354516, 2013). "Due to its involvement in several deregulated signals, the MET pathway seems to exert a pivotal role in schwannoma development and CAV1 may also exert its protumoral effect in this manner." (PMID 23354516, 2013). "We therefore selected genes that were well-established as deregulated in these tumors to verify our results and then focused on deregulated genes in other tumors, as well as in our series, that had been insufficiently studied or not studied at all in schwannomas, such as MET, AR or CAV1." (PMID 23354516, 2013).
testicular germ cell tumor (4 papers, 2018 to 2023). A germ cell tumor arising from the testis. "In previous manuscripts we reported c-MET/HGF expression and the role in testicular germ cell tumors (TGCTs) derived cell lines." (PMID 37509533, 2023).
thymoma (4 papers, 2017 to 2018). A neoplasm arising from the epithelial cells of the thymus. "Immunohistochemistry was performed to study the expression of ALK, HER2, HER3, MET, phospho-mTOR, p16INK4A, PDGFRA, PDGFRB, PD-L1, PTEN and ROS1 in type A and B3 thymomas and thymic carcinomas." (PMID 27844328, 2017). "Type A and B3 thymoma and thymic carcinoma tissues were stained with antibodies to ALK, HER2, HER3, MET, phospho-mTOR, PDGFRA, PDGFRB, PD-L1, p16INK4A, PTEN and ROS1 to identify potential targets for therapy." (PMID 27844328, 2017). "A low MET protein expression was noted in only two type A thymomas, whereas B3 thymomas and thymic carcinomas did not express MET." (PMID 27844328, 2017).
asthma (3 papers, 2017 to 2023). "The authors concluded that COX-2 and MET gene polymorphisms may play a significant role in the development of CRSwNP, which may also depend on the presence of asthma or allergy." (PMID 28400178, 2017). "There is evidence of an association of LTC4S, NOS2A, PTGDR, MET, COX-2, OSF-2, and LF polymorphisms and the risk of developing nasal polyps, especially when combined with chronic allergic rhinitis and asthma." (PMID 28400178, 2017). "TNRC6B and MET were hypermethylated in both of our ACO patients and the asthma patients in previous EWAS, while DHX30, SFXN, C19orf28, and CLCN7 were hypomethylated." (PMID 33658578, 2021).
autism spectrum disorder (3 papers, 2016 to 2021). A spectrum of developmental disorders that includes autism, and Asperger syndrome. "It has been reported that SNVs in the MET gene, causing lowered MET expression, increase susceptibility to autistic spectrum disorders (ASD) in European and North American populations." (PMID 30777867, 2019). "For example, in the forebrain, a risk allele for autism spectrum disorder (ASD) in the MET promoter, which reduces MET transcript and protein levels, is correlated with altered circuit function in typical and ASD human populations and in gray matter growth." (PMID 27595133, 2016). "In this review, we highlight, beyond the neurotrophic action, novel roles of HGF-MET in synaptogenesis during post-natal brain development and the connection between deregulation of MET expression and developmental disorders such as autism spectrum disorder (ASD)." (PMID 34179015, 2021).
carcinoma in situ (3 papers, 2016 to 2023). "Specifically, the level of c-MET expression descended from carcinoma in situ via highly atypical hyperplasia to normal mucosa." (PMID 36184713, 2023).
Chronic Lymphocytic Leukemia (3 papers, 2012 to 2014). "Other studies looked at two MET variants, R970C and T992I (also referred to as R988C and T1010I) newly identified in solid tumours and haematological malignancies: AML, chronic myelomonocytic leukaemia (CMML), and chronic lymphocytic leukaemia (CLL)." (PMID 25119536, 2014). "Moreover, the neoplastic cells in chronic lymphocytic leukemia also appear dependent upon expression of ROR1, but do not express MET, suggesting that the function ROR1 also does not require HGFR in primary tumor cells." (PMID 22403610, 2012).
clear cell carcinoma (3 papers, 2013 to 2016). "In hereditary and sporadic papillary RCC patients activating mutations of c-MET have been identified and over expression of c-MET has been also reported in clear cell carcinoma." (PMID 27322553, 2016). "In the primary-site histopathological classifications, expression of MET was seen in 6 (35 %) and matriptase in 4 (28 %) of 14 clear-cell carcinomas." (PMID 25186085, 2015). "Advanced genomic analysis of bona-fide clear cell carcinoma cell lines also support copy number changes in typical biomarkers such at MET and HNF1B and a lack of any recurrent expressed re-arrangements." (PMID 24023729, 2013).
Cognitive impairment (3 papers, 2019 to 2025). Abnormal cognition is characterized by deficits in thinking, reasoning, or remembering. "However, despite the increase of HGF, the decline of HGF receptor c-MET in the hippocampal pyramidal neurons was revealed in AD patients, which may cause reduction of HGF/c-MET signaling and cognitive impairment." (PMID 40564462, 2025).
colitis (3 papers, 2025 to 2026). Inflammation of the colon. "Moreover, capmatinib treatment eliminated the difference between EcN (BAD−904) and EcN (BAD-vector), suggesting that MET phosphorylation was responsible for the protective effects of EcN (BAD−904) on colitis." (PMID 41424360, 2026). "Consistent with the in vitro data, the phosphorylation of MET was higher in inflamed colon tissues from colitis samples than in adjacent non-inflamed colon tissue." (PMID 41424360, 2026).
colon adenocarcinoma (3 papers, 2021). "Survival analysis on GEPIA using colon adenocarcinoma data set screened 5 genes CXCL3, IL1B, IL1A, MET and TNS1 that have significant log rank p value in Kaplan–Meier survival analysis." (PMID 34083590, 2021). "For example, in BRCA, adenocarcinoma of colon (COAD) and most other tumors, all the six immune cells showed a positive correlation with HGF, indicating that immune cells were activated or recruited by the HGF/c-MET pathway." (PMID 34261467, 2021).
embryonal carcinoma (3 papers, 2020 to 2025). A non-seminomatous malignant germ cell tumor characterized by the presence of large germ cells with abundant cytoplasm resembling epithelial cells, geographic necrosis, high mitotic activity, and pseudoglandular and pseudopapillary structures formation. "Notably, c-MET availability and activation has been related to resistance to radio- and chemotherapy in different cancer types; therefore, it is conceivable to hypothesize that c-MET receptor activation could lead to refractory disease in embryonal carcinoma as well." (PMID 33212946, 2020).
genitourinary cancers (3 papers, 2017 to 2022). "For example, in the NCT02496208 phase I trial, cabozantinib, a tyrosine kinase inhibitor targeting mainly VEGFR and c-MET, is being evaluated in combination with nivolumab +/− ipilimumab in different genitourinary cancers, including mUC." (PMID 35406412, 2022).
kidney tumors (3 papers, 2019 to 2025). "The number of genes within a panel may be as few as six (e.g. BAP1, FH, FLCN, MET, SDHB, and VHL genes) though commercial genetic testing companies may offer larger gene panels (18–30 genes but including some for non-RCC kidney tumours;)." (PMID 38802529, 2024).
large cell carcinoma (3 papers, 2011 to 2019). A malignant epithelial neoplasm composed of large, atypical cells. "The large-cell carcinoma cell line A549 exhibited a moderate activation of the HER1 and IGF-1R pathways with a low activation of the c-MET and HER2 pathways, whereas the metastatic large-cell carcinoma cell line H460 showed only a very low activation of the IGF-1R pathway." (PMID 22091388, 2011).
lentivirus infection (3 papers, 2022 to 2024). Virus diseases caused by the Lentivirus genus. "Through lentivirus infection, the AS-circRNA that targets MET exon 13 could play functions in a range of cell lines, including HEK293T, HeLa, HepG2, U2OS, and HT-1080, indicating that AS-circRNAs have broad applicability to a variety of cell types." (PMID 37040525, 2023).
liver failure (3 papers, 2019 to 2025). A liver disease characterized by the liver losing or has lost all of its function. "Substantial activation of HGF/c-MET signaling is associated with hepatocyte proliferation and liver regeneration, and inhibition of these signaling pathways results in liver failure." (PMID 40325003, 2025).
lung disease (3 papers, 2021 to 2025). "Of note, a separate group of patients with lung disease other than ILDs exhibited the lowest levels of c-MET expression in T cells." (PMID 38909206, 2024).
malaria (3 papers, 2020 to 2024). Malaria is a serious and sometimes fatal disease caused by a parasite that commonly infects a certain type of mosquito which feeds on humans. "Cell traversal (hepatocytes) observed in several species of Plasmodium, the causative agent of malaria, was reported to induce HGF secretion, the activation of c-MET by hepatocytes and invasion of these cells, while other Plasmodium spp did not." (PMID 35041723, 2022). "For an initial assessment of the in vivo efficacy of the c-MET inhibitor PHA-665752, we treated mice infected with the rodent malaria parasite P. berghei." (PMID 32782246, 2020).
mesenchymal neoplasm (3 papers, 2014 to 2021). "In summary, development of a primary intracerebral mesenchymal neoplasm in a child with NCMS and hemimegalencephaly can likely be explained by specific NRAS mutant mosaicism possibly in combination with a MET germline variation, which together constitute a unique combination." (PMID 25330907, 2014).